OR13C8 (olfactory receptor family 13 subfamily C member 8)
Description:
Odorant receptor.
Synonyms: OR37H; OR9-10
Tractability: Antibody: UniProt places it where antibodies can reach, with medium confidence; UniProt predicts a signal peptide or a membrane-spanning region; its Gene Ontology location is reachable by antibodies, with medium confidence.
Gene: Protein-coding gene on chromosome 9 (104,569,168 to 104,570,130, forward strand). Ensembl gene ENSG00000186943.
Subcellular location: Cell membrane
Pathways (Reactome):
Sensory Perception: Expression and translocation of olfactory receptors
Gene Ontology:
Molecular function: olfactory receptor activity; G protein-coupled receptor activity
Biological process: detection of chemical stimulus involved in sensory perception of smell; G protein-coupled receptor signaling pathway
Cellular component: plasma membrane; membrane
Genetic constraint (gnomAD): Loss-of-function variants: 2 observed, 2.73 expected, observed/expected ratio (o/e) 0.73, 90% interval 0.29 to 1.78. That is too few expected variants to judge how well the gene tolerates losing a copy. Missense variants: 382 observed, 410.33 expected, observed/expected ratio (o/e) 0.93, 90% interval 0.86 to 1.01. Synonymous variants: 149 observed, 152.5 expected, observed/expected ratio (o/e) 0.98, 90% interval 0.85 to 1.12.
Homologues: Orthologues: chimpanzee OR13C8 (98% identical), macaque OR13C8 (94% identical), pig OR13C8 (87% identical), dog OR13C8 (86% identical), rabbit OR13C8 (84% identical), mouse Or13c25 (79% identical), rat Or13c25 (76% identical). Paralogues in human: OR2S2 (66% identical), OR13C3 (64% identical), OR13C9 (63% identical), OR13C2 (62% identical), OR13C4 (62% identical), OR13C5 (61% identical), OR13D1 (58% identical), OR2K2 (52% identical), OR13J1 (47% identical), OR2G3 (47% identical), OR2F1 (46% identical), OR2F2 (46% identical), and 80 more.
Diseases named in the same sentence as OR13C8 in open-access papers:
OR13C8 is named in the same sentence as 1 disease in open-access papers, as found by Europe PMC text mining. Sharing a sentence is not in itself a finding about the gene and the disease.
OR13C8 shares sentences with these, for which no sentence is quoted: breast carcinoma (1 paper).